BRCA2 (BRCA2 DNA repair associated)
Diseases named in the same sentence as BRCA2 in open-access papers (continued):
Sharing a sentence is not in itself a finding about the gene and the disease.
squamous cell carcinoma (4 papers, 2021 to 2025). A carcinoma arising from squamous epithelial cells. "Both penile tumors (squamous cell carcinoma) exhibited mutations in BRCA1 and FAS, as well as ARID1A, CHEK2, BRCA2, and were Human Papillomavirus (HPV) positive." (PMID 41395625, 2025). "Mutations of all; PALB2, BRCA1, BRCA2 and CHEK2 were most frequent in cutaneous squamous cell carcinomas covering ~60% of mutations in each of the genes." (PMID 34084283, 2021).
thymic lymphomas (4 papers, 2007 to 2024). "The identification of a high frequency of pathogenic Fanconi-BRCA mutations implicates this pathway in the molecular pathogenesis of human T-ALL, a possibility first raised by the spontaneous development of thymic lymphomas in Brca2-deficient mice." (PMID 31721781, 2019). "Mice homozygous for Brca2 exon 10 and 11 truncating mutations exhibit embryonic lethality, whereas a minority of homozygous mice harboring a Brca2 truncation at the 3′ end of exon 11 survive to adulthood and develop thymic lymphomas." (PMID 37934606, 2024). "Mice homozygous for a constitutive Brca2 exon 11 deletion, which abrogates approximately 45% of the Brca2 transcript, succumb to thymic lymphomas." (PMID 27037238, 2016).
Adrenocortical carcinomas (3 papers, 2012 to 2023). "There have also been clinical links between BRCA2 mutations and adrenal cortical carcinoma." (PMID 36810461, 2023).
atherosclerosis (3 papers, 2017 to 2021). A disease characterized by the build-up of fatty material and calcium deposition in the arterial wall resulting in partial or complete occlusion of the arterial lumen. "In order to get an insight about the cause and/or effect relationship of BRCA2 with atherosclerosis in ECs, we next measured BRCA2 expression levels in ECs treated with different doses (0, 5, 10, 20, 50, and 100 μg/ml) of oxLDL for 24 hr and measured BRCA1 and BRCA2 expression." (PMID 32638521, 2020). "Additionally, the data provide important clues regarding the potential susceptibility of BRCA2 mutation carriers to endothelial dysfunction, atherosclerosis, and other cardiovascular diseases." (PMID 32638521, 2020). "Accordingly, we are in the process of generating endothelial cell‐specific BRCA2 knockout mice with an ApoE−/− background and then evaluating atherosclerosis in order to delineate the cause and effect relationship between endothelial BRCA2 and atherosclerosis." (PMID 32638521, 2020). "Our overall objective is to evaluate the role of endothelial BRCA2 in endothelial function and atherosclerosis using clinically relevant, in vitro methods." (PMID 32638521, 2020). "Moreover, lipid and metabolite deregulation is observed in humans carrying either BRCA1 or BRCA2 (BRCA1/2) mutations and a genetic analysis identified BRCA2 SNPs’ association with plasma‐lipid levels, which plays an important role in endothelial dysfunction and atherosclerosis." (PMID 32638521, 2020). "In the present study, in order to understand the role of BRCA2 in endothelial dysfunction and apoptosis in atherosclerosis, we measured the expression level of BRCA2 in the aorta of the high‐fat diet versus normal diet fed ApoE‐/‐ mice." (PMID 32638521, 2020). "To date, DNA damage, apoptosis, and lipid deregulation are recognized as central pathways for endothelial dysfunction and atherosclerosis; however, the role of BRCA2 in endothelial dysfunction remains to be elucidated." (PMID 32638521, 2020). "Therefore, it is likely that BRCA2 plays an early role in cardiovascular diseases (CVDs) such as atherosclerosis (Gimbrone Jr." (PMID 32638521, 2020). "Moreover, to gain insight about BRCA2 in an atherosclerosis animal model, we measured BRCA2 in atherosclerotic plaques." (PMID 32638521, 2020). "Next, to understand the relationship between atherosclerosis, the endothelium, and BRCA2 expression, we measured BRCA2 expression levels in oxLDL‐treated ECs and observed a significantly reduced BRCA2 expression following oxLDL treatment in a dose‐ and time‐dependent manner." (PMID 32638521, 2020). "Furthermore, our data indicate that therapeutic strategies aiming to upregulate endothelial BRCA2 might be protective, particularly in the setting of vascular diseases characterized by oxidative stress such as atherosclerosis." (PMID 32638521, 2020). "To investigate the potential involvement of BRCA2 in the atherogenic process in an atherosclerosis animal model, we evaluated the expression level of BRCA2 in the aorta of the high‐fat diet fed ApoE‐/‐ (ApoEnull) mice and compared it with the expression of BRCA2 in normal diet fed ApoE‐/‐ mice." (PMID 32638521, 2020). "Thus, the BRCA2 rs9534275 SNP may be a promising drug target for therapeutic intervention against hyperlipidemia and atherosclerosis." (PMID 28982360, 2017). "In a previous study, we have found that the BRCA2 rs9534275 SNP modulated serum TC, LDL-C, ApoB concentrations, and the ApoA1/ApoB ratio in the hypercholesterolemic subjects, suggesting that the rs9534275 SNP plays an important role in the formation of atherosclerosis." (PMID 28982360, 2017).
Azoospermia (3 papers, 2016 to 2026). Absence of any measurable level of sperm,whereby spermatozoa cannot be observed even after centrifugation of the semen pellet. "Mechanistically, defects in pathways like homologous recombination and mismatch repair disrupt meiotic fidelity, causing gametogenesis failure (e.g., BRCA2-mediated azoospermia), while fostering genomic instability that drives carcinogenesis." (PMID 42311506, 2026).
basal cell carcinoma (3 papers, 2021 to 2024). A carcinoma involving the basal cells. "In an earlier study of this cohort, we reported an excess risk of basal cell carcinoma in BRCA1 and BRCA2 carriers." (PMID 38741145, 2024). "With respect to BRCA2, most tumors were cystic and basal cell carcinomas with unique keratin expression pattern." (PMID 38059556, 2024).
bile duct cancer (3 papers, 2024). "Early data showed an increased relative risk of 4.97 (95% CI 1.50-16.52) for BRCA2 carriers for developing gall bladder or bile duct cancer." (PMID 38903278, 2024). "BRCA2 mutation carriers have an increased risk of pancreatic, gallbladder, and bile duct cancers." (PMID 37966669, 2024).
bladder tumors (3 papers, 2017 to 2021). "Indeed, analyses of TCGA datasets of ovarian and bladder tumors indicated that MED12 expression levels can stratify the survival of patients with BRCA2-mutant tumors: low MED12 levels trended towards reduced survival of these patients, while high MED12 levels trended towards increased survival." (PMID 34871431, 2021).
Bloom syndrome (3 papers, 2014 to 2021). Bloom syndrome (BSyn) is a rare chromosomal breakage syndrome characterized by a marked genetic instability associated with pre- and postnatal growth retardation, facial sun-sensitive telangiectatic erythema, increased susceptibility to infections, and predisposition to cancer. "Our results showed that SQ and SCLC had overexpressed genes throughout the pathway with 10 of 11 genes overexpressed including the very important BRCA2, RAD51 paralogs and BLM (Bloom syndrome mutated)." (PMID 25325012, 2014).
chordoma (3 papers, 2018 to 2024). Chordomas are rare malignant tumors arising from embryonic remnants of the notochord in axial skeleton. "One such study performed germline whole-exome sequencing in 19 familial chordoma patients and reported defects in PALB2 and BRCA2 in 17 patients, the PALB2 mutation co-segregated with disease in one family." (PMID 38700789, 2024).
chronic lymphocytic leukemia (3 papers, 2019 to 2021). "An increased risk of chronic lymphocytic leukemia has also been demonstrated in patients with mutations of either BRCA1 or BRCA2." (PMID 33954070, 2021).
chronic pancreatitis (3 papers, 2016 to 2024). A chronic inflammatory process causing damage and fibrosis of the pancreatic parenchyma. "However, within high-risk populations (lifetime risk of 5% or more), including those with familial PC or mutations in a PC predisposition gene (e.g., BRCA2), new onset diabetes, and chronic pancreatitis, screening is proposed to improve patient outcomes while remaining cost effective." (PMID 39451765, 2024). "Similarly, accurate biomarkers are greatly needed to improve screening, particularly for those who may be at increased risk of developing PDAC: family history of PDAC, hereditary syndromes, chronic pancreatitis, type 3c diabetes, smokers, BRCA2 carriers, etc.." (PMID 26993610, 2016).
clear cell renal cell carcinoma (3 papers, 2018 to 2023). "Other variants (BRCA2 (c.5900A>G; p.(Lys1967Arg)), ATM (c.1810C>T; p.(Pro604Ser)) and MET (c.2962C>T; p.(Arg988Cys)) were found in non-syndromic patients (3/74; 4%) with clear cell renal cancer before 50 years of age." (PMID 38002934, 2023). "Ten pathogenic or likely pathogenic (P/LP) variants were identified in 11 sporadic clear cell renal cell carcinoma patients (10.38%), including rarely reported ATM (n=1), MUTYH (n=1), NBN (n=1), RAD51D (n=1), and BRCA2 (n=1)." (PMID 33062672, 2020).
ependymoma (3 papers, 2023 to 2024). A WHO grade II, slow growing tumor of children and young adults, usually located intraventricularly. "High expression of CXorf67, a DNA damage response protein that competes with BRCA2 for PALB2 interaction to impair the HR pathway, could increase sensitivity to PARP inhibitors in PFA ependymomas." (PMID 36793373, 2023).
Ewing sarcoma (3 papers, 2018 to 2025). A small round cell tumor that lacks morphologic, immunohistochemical, and electron microscopic evidence of neuroectodermal differentiation. "The molecule BSJ-01-175 is a novel potent CDK12/13 covalent inhibitor, showing high capacity in reducing RNAPII S2 phosphorylation, expression of BRCA1 and BRCA2 genes, and tumour growth of patient-derived xenograft of TC71 Ewing sarcoma cells." (PMID 39533070, 2025).
gallbladder cancer (3 papers, 2020 to 2023). "On the other hand, we also noticed that seven patients in the SYSUCC cohort with MSI-H and high TMB were deleterious BRCA2 variant carriers with colon, prostate, nasopharyngeal, or gallbladder cancer." (PMID 33054725, 2020). "For gallbladder cancer, ERBB2 and BRCA2 mutations were significantly more frequent in our cohort, while ATM mutation was enriched in the cBioPortal cohort." (PMID 32373528, 2020).
hypertrophic cardiomyopathy (3 papers, 2019 to 2026). A condition in which the myocardium is hypertrophied without an obvious cause. "The apoptotic biomarkers including Bax and cleaved caspase 3 (CC3) increased in the heart of hypertrophic cardiomyopathy, and attenuated after upregulation of BRCA2." (PMID 41625597, 2026). "The cardiac fibrosis was significantly attenuated after upregulation of BRCA2 in Ang II-induced hypertrophic cardiomyopathy." (PMID 41625597, 2026). "We hypothesized that upregulation of BRCA2 may alleviate hypertrophic cardiomyopathy." (PMID 41625597, 2026).
ischemic stroke (3 papers, 2012 to 2020). A stroke disorder caused by obstruction of blood flow to the brain, due to thrombotic (local blood clot formation) or embolic (due to a blood clot or other material traveling from another site) event. "Alternatively, variants in BRCA2 may be more relevant to the pathogenesis of other components of the composite CVD outcome utilized in SHARE (for example ischemic stroke), rather than acute MI." (PMID 22809218, 2012).
Medullary carcinomas (3 papers, 2005 to 2025). "In our study, one medullary carcinoma was identified in a group of 22 patients (4.5%) with BRCA1-related BC (F-252), whereas no tumor of this histological type was found in seven women with BRCA2-associated tumors." (PMID 16168118, 2005).
neuroendocrine neoplasm (3 papers, 2019 to 2025). Endocrine tumors, also referred to as neuroendocrine tumors (NETs), are defined by a common phenotype which is characterized by the expression of general markers (neuron specific enolase, chromogranin, synaptophysin) and hormone secretion products. "Three patients demonstrated pathogenic (class 5) BRCA1 or BRCA2 mutations – one germline-related in a mixed neuroendocrine-non neuroendocrine neoplasm (MiNEN)." (PMID 30717682, 2019). "Secondly, P-STS harbour several mutations that are atypical for well-differentiated neuroendocrine tumours and that can influence the radiosensitivity of the cell line, including mutations in BRCA1 and BRCA2." (PMID 30730850, 2019).
neurofibromatosis (3 papers, 2013 to 2025). A hereditary neoplastic syndrome in which tumors grow in the nervous system. "Few studies have shown an association with BRCA1 and BRCA2 gene mutations, along with familial syndromes such as neurofibromatosis, Maffucci syndrome, or Klippel-Trenaunay syndrome." (PMID 41181773, 2025).
oesophageal cancer (3 papers, 2010 to 2021). "In addition, the BRCA2 gene 203G>A polymorphism may be associated with susceptibility to oesophageal cancer." (PMID 25436004, 2015). "The positive expression rate of BRCA2 (50%; 37/74) in the oesophageal cancer tissues was markedly lower than that in the adjacent healthy tissues (87%; 26/30), and the difference was identified to be statistically significant (P<0.01)." (PMID 25436004, 2015). "The synergistic effect of FHIT, BRCA2, MLH1 and other relevant factors may be the molecular bases for the genesis of oesophageal cancer." (PMID 25436004, 2015). "The positive expression rates of FHIT (61%; 45/74), BRCA2 (50%; 37/74) and MLH1 (27%; 9/33) in the oesophageal cancer tissues were significantly lower than those in the healthy tissues adjacent to the cancer (97% [29/30], 87% [26/30] and 73% [25/41], respectively)." (PMID 25436004, 2015). "In addition, the BRCA2, MLH1 and FHIT genes may be involved in the genesis of oesophageal cancer in susceptible populations, and the abnormal changes in BRCA2 and MLH1 expression are important molecular events in the occurrence of oesophageal cancer in OCFH + patients." (PMID 25436004, 2015).
polyposis (3 papers, 2016 to 2024).
psychological distress (3 papers, 2021 to 2025). "Analyzing a survey data of 79 carriers of a BRCA1 or BRCA2 mutation, the majority had general psychological distress independent of cancer diagnosis in the patients’ history." (PMID 34635688, 2021). "In this study, we have shown that BRCA1 or BRCA2 mutation carriers have high levels of psychological distress irrespective of a history of cancer." (PMID 34635688, 2021). "In line with previous research, our results from the NCCN Distress Thermometer, PHQ-9 and GAD-7 demonstrated significant psychological distress among BRCA1 and BRCA2 mutation carriers, independent of a history of cancer." (PMID 34635688, 2021).
rectal adenocarcinoma (3 papers, 2020 to 2025). "Patient EOCRC#16 with both BRCA2 (a PV inherited from her father) and RECQL4 variants presented with a rectal adenocarcinoma at 39 years of age." (PMID 40429818, 2025).
small cell carcinoma (3 papers, 2015 to 2025). A neuroendocrine carcinoma composed of small malignant cells which are often said to resemble "oat cells" under the microscope. "In this case, we discuss a BRCA2 mutation carrier who initially presented with invasive ductal carcinoma of the left breast, and then developed a small cell carcinoma of the left breast several years after her initial treatment was completed." (PMID 25671134, 2015).
Squamous Cell Carcinoma of the Pancreas (3 papers, 2014 to 2025). "Here we report on a case of a 57-year-old female patient with known BRCA2 germline mutation presenting with primary squamous cell carcinoma of the pancreas as the only malignancy." (PMID 24959366, 2014).
thymoma (3 papers, 2022 to 2024). A neoplasm arising from the epithelial cells of the thymus. "Among these, a patient with BRCA2-mutated thymoma showed a significant clinical benefit from treatment with Olaparib, with imaging showing overall stabilization of her disease." (PMID 39273507, 2024). "Another issue is that patients with metastatic thymomas harboring BRCA2 mutations might experience advantages from the inhibition of PARP." (PMID 38338833, 2024).
tumor predisposition syndromes (3 papers, 2015 to 2024). "The other P/LP variants are associated with adult-onset tumor predisposition syndromes, of which BRCA2 and CHEK2 in particular have relevance in terms of surveillance for the index patients and relatives." (PMID 38415346, 2024). "Some 25–55 % of these in-family diseases are attributed to germline mutations of BRCA1 or BRCA2, and approximately 5–10 % to other known tumor predisposition syndromes." (PMID 26109557, 2015).
urothelial carcinoma (3 papers, 2022 to 2024). A malignant neoplasm derived from the transitional epithelium of the urinary tract (urinary bladder, ureter, urethra, or renal pelvis). "They detected pathogenic variants of the BRCA1 gene in 2.3% and the BRCA2 gene in 2.1% in patients with urothelial carcinoma." (PMID 35395863, 2022).
uterine sarcoma (3 papers, 2022 to 2024). "BRCA2 mutations were identified in 42 patients – 25 in the STS cohort, 10 with uterine sarcoma, six with bone sarcoma, and one with GIST." (PMID 36741731, 2022). "Furthermore, PARP inhibitors showed a similar cytotoxic effect on uterine sarcoma-derived MES-SA cell lines with NAMPT and PTEN deletions, despite the absence of abnormalities in the BRCA2 gene." (PMID 35267488, 2022).
acute leukemia (2 papers, 2019 to 2024). A clonal (malignant) hematopoietic disorder with an acute onset, affecting the bone marrow and the peripheral blood.
acute promyelocytic leukemia (2 papers, 2021 to 2024). An aggressive form of acute myeloid leukemia (AML), characterized by arrest of leukocyte differentiation at the promyelocyte stage, due to a specific chromosomal translocation t(15;17) in myeloid cells. "It is noteworthy that homozygous variants of BRCA2 and XRCC5 are associated with a greater risk of secondary acute promyelocytic leukemia (APL)." (PMID 34732266, 2021).
Alzheimer disease (2 papers, 2012 to 2025). A progressive, neurodegenerative disease characterized by loss of function and death of nerve cells in several areas of the brain leading to loss of cognitive function such as memory and language. "They include disclaimers for consumers to acknowledge prior to release of results, recommend genetic counselling and consumers can exclude specific results, including BRCA1 and BRCA2 and Alzheimer’s Disease." (PMID 39880983, 2025).
anaplastic oligodendroglioma (2 papers, 2019). A WHO grade III oligodendroglioma with focal or diffuse malignant morphologic features (prominent nuclear pleomorphism, mitoses, and increased cellularity). "Interestingly, BRCA1 was mutated in one patient diagnosed with GBM, and BRCA2 mutation was shown in one sample of anaplastic oligodendroglioma." (PMID 31882734, 2019).